CD4 (CD4 molecule)
Diseases named in the same sentence as CD4 in open-access papers (continued):
Sharing a sentence is not in itself a finding about the gene and the disease.
AIDS (continued). "Patients with HIV/AIDS should be consistently followed up and the CD4 T-cell count regularly monitored, and timely and early antiretroviral therapy initiated in order to achieve a better survival rate." (PMID 27399071, 2016). "HIV-1 mainly infects CD4+ lymphocytes and monocyte-derived macrophages and consequently leads to the onset of AIDS and AIDS-related symptoms." (PMID 27478681, 2016). "HIV/AIDS, which is characterized by reduced levels of CD4+ T cells, offers a unique opportunity to understand the role of immune system in TB pathogenesis." (PMID 27709522, 2016). "An HIV infected patient is seropositive but will only develop AIDS symptoms when the CD4 T-helper lymphocyte count (CD4) is less than 200 cells/mm." (PMID 26946205, 2016). "This monocentric study included AIDS patients with CD4 <200 cells/μL, age 18 years or older, and a minimum of one edentulous space requiring implant." (PMID 27747712, 2016). "In this context, we compared the percentage of patients presenting with AIDS, as well as the CD4-cell count at entry to specialized care among different migrant populations and non-migrants in a long term cohort study of HIV positive patients in Germany." (PMID 27927190, 2016). "TSOL has only been investigated patchily with contradictory results in people living with HIV/AIDS and the impact of CD4+ counts, HAART duration and HIV stages on the incidence of T. solium and the exacerbation of NCC have not been explored so far." (PMID 27903304, 2016). "HIV-1 RNA load at 6 months and changes in CD4 count from 6 to 36 months after start of ART are prognostic for AIDS in patients who have survived 3 years of ART." (PMID 27025828, 2016). "In summary, we showed the significant depletion of CD4+ T cells and decline of CD4/CD8 ratios in peripheral and GI tract lymphatic tissues particularly in IELs in the SIV-infected macaques with AIDS-associated diarrhea." (PMID 27708644, 2016). "In this perspective, we did not found any differences in adjusted risk of virological failure according to the PI/r given in those patients starting cART with CD4 counts less than or equal to 350 cells/mm3 or AIDS." (PMID 27348592, 2016). "Studies of large HIV-positive populations present lower lymphocyte CD4+ count and shorter time to AIDS for older patients, which is well in line with higher rate of late presenters among older patients in most observational cohorts." (PMID 26744599, 2016). "HIV infection has been related to HPA axis dysfunction primarily due to opportunistic infections (i.e., patients with AIDS and a very low CD4 cell count)." (PMID 27006656, 2016). "The allergic history, opportunistic infection, viral load, CD4 cell count, high globulin and low albumin were the risk factors correlated with death in HIV/AIDS patients with drug eruption." (PMID 27796328, 2016). "Individuals at the AIDS stage (p = 0.007), with lower CD4+ T cell count (p = 0.002) and higher viral load (p = 0.021) were more likely to present ADR-CRM." (PMID 27119150, 2016). "Older age, male sex, injecting drug use transmission, AIDS, and low CD4 count and detectable viral replication ten years after starting combination antiretroviral therapy were associated with higher subsequent mortality." (PMID 27525413, 2016). "The 1993 expanded AIDS surveillance case definition measured DP if persons present with a CD4 cell count < 200 cells/μl and/or with an AIDS defining disease." (PMID 27802839, 2016). "We therefore choose the definitions of ‘low CD4 counts (LC) and very low CD4 count (VLC) to define people diagnosed with AIDS and/or CD4 count ≤350 cells/mm3 or ≤200 cells/mm3, respectively." (PMID 27348592, 2016). "Clinically, HIV-2 patients have a higher CD4 cell count at the time of AIDS, and generally have a longer survival after AIDS." (PMID 26821323, 2016). "For example, we excluded individuals who received cART in EHI because of low CD4+ cell counts or AIDS." (PMID 26636925, 2016).
AIDS (continued). "Despite significant investment in increasing awareness concerning HIV care and advances in treatment, many patients still present late in their HIV disease with either an AIDS defining illness or a CD4 count of <200 cells/uL." (PMID 27142869, 2016). "The BD FACSPrestoTM Near-Patient CD4 Counter was developed to expand HIV/AIDS management in resource-limited settings." (PMID 27483008, 2016). "The AIDS group had severely depressed CD4+ cell counts compared to the other groups (χ2 = 5.6, p = 0.01)." (PMID 26956496, 2016). "In our study, the T.gondii DNA was detected in (60 %) of the seropositive toxoplasmosis HIV/AIDS patients with CD4 count less than 100 cells/μl." (PMID 27083153, 2016). "Although CD4+ T-cell counts of 200/μL are defined as HIV-induced AIDS, additional studies are needed to determine what declining levels of CD4+ T cells predisposes HIV-1-infected individuals to developing M. tb co-infection or active TB." (PMID 26959228, 2016). "Meningitis due to Cryptococcus, coccidioidomycosis, histoplasmosis, or other fungal infection represents an AIDS-defining event and occurs typically with very low CD4 counts." (PMID 27579194, 2016). "Cryptosporidium parvum, Cyclospora cayetanensis, Isospora belli and Microsporidia are often recognized as opportunistic parasites in HIV/AIDS patients because they tend to be present when the CD4+ T cell counts are below 200 cells/μl." (PMID 26754404, 2016). "Summaries of extended linear mixed models (with marginal multivariate‐normal distribution) fitted to square‐root transformed pre‐antiretroviral therapy CD4 measurements from the Concerted Action on SeroConversion to AIDS and Death in Europe dataset." (PMID 26555755, 2016). "Summaries of multivariate‐t distribution models fitted to square‐root transformed pre‐antiretroviral therapy CD4 measurements from the Concerted Action on SeroConversion to AIDS and Death in Europe dataset." (PMID 26555755, 2016). "Future records of PMTCT services should correlate the occurrence of any non-AIDS condition with the HIV-positive pregnant woman’s CD4 count and WHO stage of illness and with the baby’s HIV status." (PMID 27246792, 2016). "From the plots we can see that in most sites the proportions of new enrollees with low CD4 count (<200 cells/μL) and clinical AIDS has decreased over time." (PMID 26963255, 2016). "Advanced immunosuppression with CD4 T cell count ≤200 cells/mm3 or development of an AIDS defining condition prior to starting ART results in a four-fold higher incidence of oral warts as the immune system recovers." (PMID 26930571, 2016). "An association between symptomatic acute primary infection and a worse prognosis in terms of decline in CD4+ T cells count and progression to AIDS has been described." (PMID 27769179, 2016). "In summary, both IL-6 and D-dimer independently predict the risk of serious non-AIDS conditions or death among HIV-positive patients with suppressed virus and moderate to high CD4 cell counts." (PMID 27171281, 2016). "Longitudinal treatment outcomes spanning the entire HAART era were also analyzed to evaluate CD4 trajectories and development of new AIDS events during long-term HAART." (PMID 27449671, 2016). "Following an HIV infection, clinical symptoms defining AIDS can develop within months after infection, but it can also take a decade for AIDS symptoms to appear, depending on the amount of virus continuously produced by CD4+ T cells." (PMID 27017509, 2016). "Untreated HIV type 1 (HIV-1) infection is characterized by progressive decline of CD4+ T cells, resulting in the development of AIDS." (PMID 27525551, 2016). "Most patients from the Serbian cohort had a prior AIDS diagnosis at cART initiation and mean baseline CD4+ T-cell counts below 200 cells/mm3." (PMID 26939611, 2016).
AIDS (continued). "In the CCASAnet cohort, patients initiating cART immediately separate into two groups, higher CD4 and lower CD4 with AIDS status at initiation, and patients initiating cART with AIDS have increased probability of death." (PMID 26963255, 2016). "Anti-Tat antibodies have been shown to be associated with slower progression to AIDS, and vaccination with Tat protected HIV-infected subjects from CD4+ T cells decline and immune dysfunction." (PMID 27450538, 2016). "Our findings suggest that drugs such as Maraviroc or gene therapy targeting CCR5 interaction with HIV gp120 can not only prevent R5-mediated HIV-1 entry, they can also reduce Env-mediated CD4 T cell depletion and AIDS disease progression." (PMID 27026376, 2016). "Sustained VL suppression is essential to reduce long-term morbidity in HIV-infected patients, as demonstrated by the lower proportion of AIDS events and improved CD4 cell reconstitution after ≥10 years of continuous VL suppression." (PMID 27449671, 2016). "The primary endpoint of the study did not reveal any differences in disease progression towards onset of AIDS (defined as a drop of CD4 counts below 200 cells/ml or the onset of a clinical AIDS-defining condition)." (PMID 26812052, 2016). "We also assessed the ability of lentivirus delivered Cas9/gRNA in editing the HIV-1 genome present in PBMC’s and CD4+ T-cells obtained from HIV-1+ patients during routine visits to the Temple University Hospital AIDS clinic." (PMID 26939770, 2016). "This study follows the definition of the UK Collaborative HIV Cohort (UK CHIC), which defines “late presentation” as one in which the CD4 cell count is below that when treatment should be initiated (currently CD4 cell count <350 cells/mL or AIDS)." (PMID 26999167, 2016). "Several authors have delved into the realm of implantology in the HIV-positive patient, but there is only one study specifically for the AIDS patient (CD4 count <200 cells/μL), though patients were followed up for 6 months only." (PMID 27747712, 2016). "hOCT1 is also known to be expressed in most immune system cells, including a major target in AIDS therapy, CD4+ T cells." (PMID 27445813, 2016). "are a common feature in HIV/AIDS persons especially when the CD4+ T cell counts fall below 200 cells/μl." (PMID 26754404, 2016). "It should be noted though that the frequency of seroconversion illnesses was low, and similar in both groups, and that those who started treatment in EHI because of an AIDS diagnosis and/or low CD4+ cell counts have been excluded." (PMID 26636925, 2016). "Primary endpoint was time to progression to an AIDS-defining condition or to a CD4-count below 200 cells/μl." (PMID 26812052, 2016). "First, the primary endpoint of the study, “progression to AIDS”, contains both a laboratory surrogate marker (CD4 counts), as well as a purely clinical endpoint (onset of an AIDS-defining condition)." (PMID 26812052, 2016). "Almost 90 % overall were in CDC category A, and all but 1.7 % had VL above 400 copies at baseline; 10.2 % of group 3 had AIDS by CD4 count <200 at baseline." (PMID 26463526, 2016). "The findings about the associations between mental health and physical health status, as measured by time since diagnosis, CD4 counts, number of somatic symptoms, and disease courses (AIDS diagnosis), are fragmented as well." (PMID 27082749, 2016). "Viral replication, lower CD4 count, prior AIDS, and transmission via injecting drug use continue to predict higher all-cause and AIDS-related mortality in patients treated with combination antiretroviral therapy for over a decade." (PMID 27525413, 2016). "Weight loss has been related with impaired immune function and plays a predictive role in HIV disease progression to AIDS independently of powerful indicators, such as low CD4 cell count." (PMID 27468351, 2016).
AIDS (continued). "The CD4 count in patients harboring parasites was 195.47 cells/μL, which is well below the WHO immunological criteria for severe HIV infection and AIDS, defined as CD4 count below 350 cells/μL." (PMID 27795876, 2016). "Utilizing the PIMATM Point-of-care (POC) CD4+ T-cell enumeration technology will also supports the National and Army AIDS programs strategies to control HIV infection and its transmission." (PMID 27166955, 2016). "In later stages of infection, X4-tropic viruses emerge and are thought to be responsible for the accelerated decline of CD4 T cells and AIDS progression." (PMID 27026376, 2016). "Okoye19 found a similar prevalence of ECG abnormalities in 80% of AIDS patients with CD4 cell counts < 200 cells/mm3, 60% of HIV-positive subjects with CD4 cell counts > 200 cells/mm3 and 35% of HIV-negative healthy controls." (PMID 27841913, 2016). "For example, the criteria for HAART initiation in 2013 in Spain was having a CD4 count of < 500 cells/μL in asymptomatic patients or presenting an AIDS-defining illness." (PMID 26716982, 2015). "The association of low plasma IGF1 (or IGF2) and high IGFBPs with HIV progression (AIDS, low CD4 T cell counts) have been well established." (PMID 25890304, 2015). "We repeated the analyses for the subset of individuals with CD4 count ≤ 350 cells/mm3 or clinical AIDS." (PMID 26348214, 2015). "Among patients with initial CD4 cell counts less than 350 cells/μL, those who were older, female, native, baseline tuberculosis positive, baseline AIDS stage and had a lower initial CD4 cell count were more likely to receive ART." (PMID 26213959, 2015). "This trend is not likely to be associated with the delayed HIV diagnosis, as the number of patients with asymptomatic infection at diagnosis increased over time, and increases in the CD4 count at nadir and the number of AIDS cases were stable." (PMID 26297538, 2015). "Forty-one percent of subjects had a CD4 cell count < 200 cells/μL, 8.6% presented clinical AIDS and 62.6% received ART." (PMID 26703689, 2015). "HIV-1 is the pathogen of the acquired immunodeficiency syndrome (AIDS) in humans, with the depletion of CD4+ lymphocytes, the major target cells of viral infection in vivo, eventually resulting in defective cellular immunity." (PMID 25838832, 2015). "Here, we state our point of view on the role of blood stem and progenitor cell in chronic HIV infection, with a focus on memory CD4 T-cell in the context of HIV/AIDS eradication and cure." (PMID 26300920, 2015). "Early HAART treatment in patients with a higher CD4+ T-cell count significantly delayed progression to AIDS in these patients." (PMID 26413133, 2015). "The presence of lymphopenia at the expense of T CD4+ lymphocytes can be an important confounding factor, since most of the treating physicians associate this finding with HIV/AIDS, as in this case." (PMID 26019385, 2015). "Only a few patients had an AIDS diagnosis prior to the enrollment in the study (12.3%), consistently with the nadir of CD4+ T cells count (342/μl, IQR: 183–508)." (PMID 25933346, 2015). "The effect of CD4+ T cell count on IPs among pediatric HIV/AIDS patients in ZMH from August 5, 2013 to November, 2013, Addis Ababa, Ethiopia (N = 180)." (PMID 25658626, 2015). "There were a number of large cohorts showing that delaying initiation of ART until CD4 count fell below 350 cells/mm3 was associated with a greater risk of AIDS-defining illness and/or death than initiating ART at CD4 cell count greater than 350 cells/mm3." (PMID 25908935, 2015). "IRIS is a consequence of the replacement of CD4+ cells in AIDS patients or of the restoration of the trafficking of immune system cells following plasma exchange (PLEX) to accelerate the removal of natalizumab in MS patients." (PMID 25972864, 2015). "In a similar vein, stimulant use among PLWHA was found to predict faster HIV disease progression, decrease in CD4 counts and AIDS related mortality." (PMID 25933422, 2015).
AIDS (continued). "Overall, 48% of participants (n=4274) initiated ART with a CD4 cell count <200 cells/mm3 or a baseline AIDS-defining illness." (PMID 26443752, 2015). "Although candidiasis is one of the most common lesions in HIV/AIDS, its development increases with decrease in CD4+ count." (PMID 25745611, 2015). "It has been suggested that twice as many Clostridium difficile infections (often treated with MTZ) occur in HIV-positive patients (notably with AIDS or lower T CD4 counts or post-antibiotic exposure) than in HIV-negative patients." (PMID 26691198, 2015). "Although highly variable, survival in patients with acquired immune deficiency syndrome (AIDS)-associated PML has been linked to specific patient characteristics, JC viral load in cerebrospinal fluid (CSF), and underlying immunologic function, such as low CD4+ cell count at disease onset." (PMID 25771865, 2015). "The results of our study also suggest that age and baseline CD4+ T-cell count were critical factors that determine the rate of progression of HIV to AIDS." (PMID 26413133, 2015). "In a sub-analysis focussing exclusively on participants initiating ART in the time period 2008 to 2012 (n=4048), 68% of participants (n=2,751) initiated ART with a CD4 cell count <350 cells/mm3 or with a baseline AIDS-defining illness." (PMID 26443752, 2015). "Individuals with non-R5 viruses had more advanced HIV infection, with lower CD4 cell counts (median 147 versus 330/mm3), lower nadir CD4 cell counts (median 17 versus 102/mm3) and more frequent AIDS status (63.6% versus 45.3%) than individuals with R5 viruses." (PMID 26714012, 2015). "Among the 664 participants initiating ART in 2012, the proportion with a baseline CD4 cell count <350 cells/mm3 or an AIDS-defining illness was 48% (n=316)." (PMID 26443752, 2015). "This method makes use of available clinical markers such as CD4+ cell counts over the course of HIV infection and any concurrent AIDS associated diagnosis." (PMID 26512688, 2015). "We report here the virological, immunological and inflammatory markers up to 48 weeks of follow-up and the time to require resuming ART (CD4<350/μl or AIDS events) in the long-term follow-up." (PMID 26186440, 2015). "Given that we have assumed an increased risk for non-AIDS deaths, when healthcare centre visit costs were also increased by 1.5-fold in diagnosed MSM with CD4 count <200 cells/mm3, the estimated lifetime healthcare costs rose to £404,500." (PMID 25901355, 2015). "In particular, the model was required to predict the evolution of a long lived metastable state of low level viral infection, which ultimately breaks down to uncontrolled viral growth and a precipitous fall in CD4+ T cells, two hallmarks of AIDS." (PMID 25837979, 2015). "Distribution and Outcome of CMV End Organ Diseases across the strata of CD4 count among the participating HIV/AIDS patients having CMV EODs (N = 162)." (PMID 25679798, 2015). "We describe a Bayesian approach, discuss computational issues, and apply the proposed methods to CD4 count data from a pediatric AIDS clinical trial." (PMID 25762065, 2015). "How to utilize anti-inflammatory drug or immunotherapy to reprogram memory CD4 T-cell function whereby to reconstitute patient immunity is an imperative task in both the development of AIDS vaccine and cure." (PMID 26300920, 2015). "Early AIDS-associated death is the main result of treatment failure and is predicted by older age, history of IDU, lower CD4 count at therapy switch, and medication adherence levels <95%." (PMID 26512561, 2015). "Another MAA begins by using CD4+ cell count information to exclude immuno-compromised individuals with AIDS." (PMID 26512688, 2015). "Mucosal and peripheral depletion of CD4+ T-cells constitutes the most important marker of AIDS progression." (PMID 26291824, 2015). "AIDS is characterized by low CD4+ T cell counts (below 200 cells/μL), hemogram abnormalities, chronic immune activation, and the occurrence of opportunistic infections." (PMID 29061947, 2015).